ZNF273 (zinc finger protein 273)
Description:
May be involved in transcriptional regulation.
Synonyms: HZF9
Tractability: PROTAC: ubiquitination databases record sites on it.
Gene: Protein-coding gene on chromosome 7 (64,870,172 to 64,930,981, forward strand). Ensembl gene ENSG00000198039.
Subcellular location: Nucleus
Subcellular location (Human Protein Atlas): Nucleoplasm
Pathways (Reactome):
Gene expression (Transcription): Generic Transcription Pathway; Regulation of endogenous retroelements by KRAB-ZFP proteins
Gene Ontology:
Molecular function: protein binding; DNA-binding transcription factor activity, RNA polymerase II-specific; RNA polymerase II cis-regulatory region sequence-specific DNA binding
Biological process: regulation of DNA-templated transcription; regulation of transcription by RNA polymerase II
Cellular component: nucleus
Genetic constraint (gnomAD): Loss-of-function variants: 16 observed, 18.84 expected, observed/expected ratio (o/e) 0.85, 90% interval 0.57 to 1.29. The upper end of that interval is the gene's LOEUF score, 1.29, which puts it in group 5 of 6, group 1 being the genes least tolerant of losing a copy. Missense variants: 576 observed, 676.93 expected, observed/expected ratio (o/e) 0.85, 90% interval 0.79 to 0.91. Synonymous variants: 199 observed, 226.46 expected, observed/expected ratio (o/e) 0.88, 90% interval 0.78 to 0.99.
Homologues: Orthologues: macaque ZNF273 (86% identical). Paralogues in human: ZNF680 (67% identical), ZNF92 (66% identical), ZNF737 (64% identical), ZNF66 (63% identical), ZNF723 (63% identical), ZNF98 (63% identical), ZNF430 (62% identical), ZNF675 (62% identical), ZNF257 (61% identical), ZNF431 (61% identical), ZNF730 (61% identical), ZNF626 (61% identical), and 6 more.
Diseases named in the same sentence as ZNF273 in open-access papers:
ZNF273 is named in the same sentence as 7 diseases in open-access papers, as found by Europe PMC text mining. Sharing a sentence is not in itself a finding about the gene and the disease. The quoted sentences say what the papers report.
breast carcinoma (3 papers, 2019 to 2024). "A number of these, such as CEBPB, ZNF117 and ZNF92, have been previously proposed as breast cancer markers and ZNF273 and ZNF727 have been reported as breast cancer hub genes." (PMID 38561804, 2024). "In the breast cancer tissue panel (normal = 5, tumor = 43), we found that four KRAB‐ZNFs (ZNF205, ZNF273, ZNF485, ZNF695) were significantly upregulated in tumor tissue." (PMID 30444046, 2019). "Finally, these factors (ZNF273, ZNF485, ZNF695, ZNF643, and ZNF789), together with ZNF714, had significantly increased mRNA levels in the DNA methylation cluster 5 identified for breast cancer, which also coincides with the basal‐like subtype and the lowest overall DNA methylation level." (PMID 30444046, 2019).
kidney cancer (1 paper, 2015). Primary or metastatic malignant neoplasm involving the kidney. "However, there is a strong correlation between high expression of ZNF273 and ZNF683 with poor survival rates in colorectal and kidney cancers, respectively." (PMID 25994056, 2015).
metastatic tumors (1 paper, 2026). "Intersection of significantly mutated genes with differentially expressed genes identified a focused 29-gene overlap, including RYR1 and ZNF273, that marks these convergent axes and distinguishes metastatic from non-metastatic tumors." (PMID 41573907, 2026).
cancer (3 papers, 2015 to 2021). A tumor composed of atypical neoplastic, often pleomorphic cells that invade other tissues. "For example, ZNF273 was correlated with four motifs in CRC and ZNF683 was correlated with nine motifs in KIRC; neither of these TFs has ever been associated with cancer." (PMID 25994056, 2015).
neurological disorders (1 paper, 2025). "ZNF273 belongs to the zinc finger protein family, which plays a crucial role in brain development and has been implicated in various neurological disorders." (PMID 41333685, 2025).
tumor (1 paper, 2019). "Within these 148 comparisons, significantly higher expression in normal tissues compared to tumor tissues was observed only in six cases (ZNF138 in KIRC and THCA, ZNF200 in THCA, ZNF273 in PRAD, ZNF485 in THCA, and ZNF789 in KICH)." (PMID 30444046, 2019).
ZNF273 also shares sentences with these, for which no sentence is quoted: psoriasis (1 paper).